SLC6A4 (solute carrier family 6 member 4)
Diseases named in the same sentence as SLC6A4 in open-access papers (continued):
Sharing a sentence is not in itself a finding about the gene and the disease.
depression (continued). "One the one hand, one meta-analysis concluded that ELS significantly interacted with presence of the S allele in 5-HTTLPR of SLC6A4 to predict greater stress sensitivity and risk of depression." (PMID 31428006, 2019). "The genotype-guided recommendations of CYP2D6, CYP2C19, and SLC6A4 were associated with significantly higher measures of anxiety and depression in comparison to treatment as usual." (PMID 30837869, 2019). "Studying ACE score in relationship with SLC6A4 S-allele and depression severity is also important, as there are gene and environment interactions." (PMID 30837869, 2019). "Associations between the SLC6A4 polymorphisms and PD symptoms including depression, intellectual impairment, tremor and rigidity were analyzed." (PMID 31024427, 2019). "Overall, most of the studies found that BDNF and SLC6A4 hypermethylations were associated with depression." (PMID 30718449, 2019). "Generally, most studies found BDNF and SLC6A4 hypermethylation to be associated with MDD or depression." (PMID 30718449, 2019). "Positive associations between SLC6A4 methylation modifications and depression have also been identified in many studies in this review and previous reviews." (PMID 30718449, 2019). "In humans, a lesser-expressing form of Slc6a4 has been associated with an increased risk of developing depression in response to early-life stress." (PMID 30279456, 2019). "This is also the first study to examine the potential modifying effects of other polymorphisms throughout the SLC6A4 gene on the depression-methylation association." (PMID 30180828, 2018). "In contrast, three studies found positive associations between peripheral SLC6A4 methylation in blood and depression in Caucasian (n = 57) and Asian adults (n = 151; n = 84), two of which had overlapping assay regions with our study." (PMID 30180828, 2018). "It is known that depression presents a strong linkage to nicotine dependence and SLC6A4 is strongly associated with the pathophysiology of tobacco use, namely at the level of serotonin reuptake." (PMID 29927965, 2018). "Five SLC6A4 polymorphisms were found to potentially modify the association between depression and DNA methylation at multiple CpG units." (PMID 30180828, 2018). "Previous studies that have investigated the extent to which SLC6A4 genotype can influence DNA methylation in the context of depression, have focused primarily on the 5-HTTLPR polymorphism." (PMID 30180828, 2018). "Modifying effects of 5-HTTLPR genotype on the association between SLC6A4 methylation and several depression-related adversities, including childhood abuse and stress, have been demonstrated previously." (PMID 30180828, 2018). "Differential SLC6A4 methylation at the promoter CpG island has been correlated with risk factors and adversities related to depression." (PMID 30180828, 2018). "Previous evidence suggests that the serotonin transporter gene (SLC6A4) is associated with the structure of brain regions that are critically involved in dysfunctional limbic-cortical network activity associated with major depressive disorder (MDD)." (PMID 27505229, 2016). "With regard to the 5-HT system, an increasing number of studies have found associations between peripheral methylation in the SLC6A4 gene and both early life adversity and depression." (PMID 25781010, 2015). "For example, the s-variant of the serotonin transporter gene, SLC6A4, is associated with anxiety and depression and the SNP we identified (rs4251417) has been implicated in the etiology of depression and anxiety disorders." (PMID 26111525, 2015). "Given that short allele carriers exposed to life stress are more likely to show depressive symptoms, these findings are in line with previous studies that associated higher SLC6A4 methylation with depression." (PMID 25995833, 2015). "Recently, methylation of the SLC6A4 promoter was shown to be associated with early childhood adversity in adults with major depression." (PMID 25520635, 2014).
depression (continued). "The serotonin transporter plays an important role in emotion and social relations [reviewed by Canli and Lesch (2007)], and interestingly, a gene variant conferring low slc6a4 function was reported to increase depression resulting from abuse in pregnant women." (PMID 23641204, 2013). "The short variant of the 5-HTTLPR of SLC6A4 (S) has been associated with traits related to anxiety and depression." (PMID 24286069, 2013). "Nevertheless, SLC6A4 methylation from blood derived cells was previously associated with psychiatric disorders such as depression and alcoholism in humans." (PMID 22745770, 2012). "These authors also performed a haplotype analysis with the polymorphisms linked to rs12150214 and found that this region of the SLC6A4 gene was associated with not only depression but also elevated IL-6 levels in the study subjects." (PMID 22911682, 2012). "Various observational and experimental studies have shown that SLC6A4 and its variations are involved in susceptibility to several psychiatric conditions in humans and mice, including depression and anxiety." (PMID 22911682, 2012). "The serotonin transporter gene SLC6A4 rs3813034 was initially found to be significantly associated with panic disorder and showed a significant association with antidepressant treatment response in patients with major depressive disorder." (PMID 41300755, 2025). "In addition, qPCR analysis showed an upregulation in the expression of inflammatory markers like IL‐1β, TNF‐α, and the depression‐associated gene SLC6A4 after hormonal treatment and TBI exposure." (PMID 39665190, 2025). "The serotonin transporter (5-HTT or SLC6A4) gene has been widely studied in relation to depression, as it encodes the protein responsible for transporting serotonin, a neurotransmitter involved in multiple functions but widely accepted for its role in mood regulation." (PMID 40319044, 2025). "Specifically, we investigated the genetic and epigenetic correlates of key stress-associated genes (NR3C1, NR3C2, FKBP5, GILZ, SLC6A4) with psychological characteristics (depression, anxiety, and stress) often included in DD diagnostic criteria, as well as with brain EEG findings." (PMID 38391714, 2024). "Furthermore, SLC6A4 gene polymorphisms have been associated with the pathogenesis and risk of depression." (PMID 37581520, 2024). "The BDNF, COMT, and SLC6A4 genes were selected as they have been previously implicated in signaling pathways that are potentially disrupted in depression and can therefore be considered candidate genes for depression." (PMID 37754245, 2023). "Additionally, SLC6A4 is a typical and mature anti-depressant drug target; its gene polymorphism is associated with depression and anxiety." (PMID 37570816, 2023). "Numerous studies have revealed association between SLC6A4 DNA methylation and depression." (PMID 36583185, 2022). "Stress and depression are primarily associated with epigenetic alterations in genes involved in regulating resilience and/or susceptibility to stress, including stress response-related genes (crf) and genes involved in neurotransmission (SLC6A4)." (PMID 35865627, 2022). "SLC6A4 has been shown to be associated with psychiatric disorders, can be used to explain the association between major depressive disorder and suicidal tendencies, and is the most promising therapeutic target for future depression research." (PMID 35770096, 2022). "Thus, the objective of this study was to examine the association of DRD4 and SLC6A4 genetic polymorphisms with depression or anxiety in HD patients in Jordan." (PMID 33784353, 2021). "The effect of DRD4 and SLC6A4 polymorphisms on depression adjusting for other covariates." (PMID 33784353, 2021). "Nevertheless, SLC6A4 appears to be associated with depression, but in a more complex fashion." (PMID 33765975, 2021). "Third, statistical power could be too low to detect associations between SLC6A4 methylation and age at depression onset or depression severity." (PMID 33765975, 2021).
depression (continued). "Genotype and allele frequencies of DRD4 and SLC6A4 polymorphisms by depression and anxiety status." (PMID 33784353, 2021). "Age and BMI were significantly associated with SLC6A4 methylation and/or age at depression onset." (PMID 33765975, 2021). "It has been shown that ELS caused SLC6A4 methylation and that reduced SLC6A4 expression allowed serotonin to accumulate in the synaptic gap, thereby impairing normal serotonin function and leading to depression." (PMID 34890365, 2021). "However, we cannot rule out the possibility that there are small associations between SLC6A4-methylation and age at depression onset." (PMID 33765975, 2021). "Therefore, in this study we used genotyping data from a prospective, multicenter trial to evaluate the association between persisting depression and the two I/D polymorphisms in the SLC6A4 and ACE gene located on chromosome 17." (PMID 32367400, 2020). "It is encoded by SLC6A4 which has been implicated in risk of depression following emotional trauma." (PMID 32012861, 2020). "Similarly, genetic downregulation of the 5-HT transporter gene (Slc6a4/SERT) causes depression-related behaviors that have a developmental origin." (PMID 30279456, 2019). "Moreover, reduced Slc6a4/SERT functionality, as reported in human carriers of low-functioning Slc6a4/SERT alleles, has been linked to anxiety-related behavioral traits and vulnerability to childhood trauma and depression." (PMID 30279456, 2019). "The aim of this study was to determine whether genetic variation in the SLC6A4 gene influences promoter DNA methylation, and whether these are associated with depression status." (PMID 30180828, 2018). "We present evidence for genotype-dependent associations between SLC6A4 methylation and depression." (PMID 30180828, 2018). "Depression was found to be associated with the rs3794808 variant, affecting the SLC6A4 gene." (PMID 29927965, 2018). "Mutations in the Slc6a4 promoter affect the rate of serotonin uptake and are therefore associated with numerous diseases like sudden infant death syndrome, and propensity to post-traumatic stress disorder or susceptibility for depression." (PMID 28337123, 2017). "The serotonin transporter-linked polymorphic region (5-HTTLPR) of the serotonin transporter gene (SLC6A4) S allele is linked to pathogenesis of depression and slower response to selective serotonin reuptake inhibitors (SSRIs); depression and SSRIs are independently associated with bone loss." (PMID 28892067, 2017). "Such a finding is in line with the hypothesis that SLC6A4 methylation represents risk for developing depression and that other biological or social risk factors, as well as protective factors, need to be taken into account too." (PMID 25781010, 2015). "In a similar approach, the objective of the present study was to evaluate, in a sample of older women, the association of anxiety disorders and/or depression with a specific DNA methylation according to SNVs in four candidate genes: SLC6A4, BDNF, OXTR, and APOE." (PMID 26175754, 2015). "It has been documented that a decreased level of serotonin may be responsible for mood disorders, and the 5HTT (SLC6A4) gene that encodes the serotonin transporter is one of the most frequently studied genes in depressive disorders." (PMID 25826396, 2015). "Candidate genes of interest implicated in depression and social affect were examined, including the serotonin transporter slc6a4 and receptors for the neuropeptides oxytocin (oxtr) and vasopressin [the main receptor, avpr1a; for reviews, see Beck (2008); Neumann and Landgraf (2012)]." (PMID 23641204, 2013). "And finally, SLC6A4 encodes the serotonin transporter, which plays a pivotal role in the monoamine hypothesis of depression." (PMID 24278217, 2013). "The SLC6A4 gene codes for the serotonin transporter gene and plays an important role in the monoamine hypothesis of depression, according to which depressive phenotypes are caused by an imbalance in monoamines like serotonin." (PMID 24278217, 2013).
depression (continued). "Furthermore, the variation of human serotonin transporter (5-HTT, SLC6A4) gene was suggested to exert a modulating effect on the association between early life stress and the risk for depression." (PMID 21857948, 2011). "We detected three polymorphisms (SLC6A4 intron 2 VNTR, 2 COMT polymorphisms) which may contribute to the genetic susceptibility to major depression, however, only one (SLC6A4) which held up to multiple comparison corrections." (PMID 16822313, 2006). "For example, DNA methylation might be a potential link between environmental factors and the occurrence of depression; a review showed that BDNF and NR3C1 gene methylation levels were associated with depression, but the relationship between SLC6A4 and depression was found to be contradictory." (PMID 37181891, 2023). "Hence, the Ile185Met mutation of GPM6B might be associated with major depressive disorder through interactions with SLC6A4." (PMID 37511534, 2023). "So, the functional role and the interactive effect of 5-HTTLPR/rs25531/rs25532 polymorphisms with SLC6A4 promoter methylation could be characterized in future studies in subjects affected by depression, or by alcohol or drug dependence and under antidepressants." (PMID 33923526, 2021). "In post-stroke patients, high methylation levels of the SLC6A4 promoter have been associated with both post-stroke depression (PSD) and worsening of depressive symptoms suggesting that DNA methylation might modulate the response to stress with implications for physical function and quality of life." (PMID 33923526, 2021). "Increased methylation of the whole CpG island or specific CpG sites in the promoter region of the SLC6A4 gene has already been associated with decreased transcription rate, lower mRNA concentrations, SLEs and recent depressive symptoms, family history of depression as well as post-stroke depression." (PMID 33765975, 2021). "Therefore, any disturbances of SLC6A4 may contribute to depression pathogenesis, by causing dysregulation of the serotonergic system." (PMID 33804455, 2021). "Furthermore, SLEs are associated with SLC6A4 methylation and early-onset depression." (PMID 33765975, 2021). "In addition to PNN, the serotonin system plays a critical role in the pathogenesis of stress, but therapies that target the stress and depression associated genes such as Tph2 and Slc6a4 (SERT) to modulate serotonin reuptake and degradation have no obvious effect in clinical trials." (PMID 33408739, 2020). "Incidentally, it is noteworthy that in exposed subjects developing affective and cognitive disorders, we could detect an association between IR and polymorphisms of the serotonin transporter gene SLC6A4, being serotonin, the main neurotransmitter involved in depression." (PMID 32316206, 2020). "SLC6A4 hypermethylation has typically been described as independently associated with early stress and depressive disorders; though, very few studies address whether methylation can mediate the interaction between stress and 5HTTLPR in predicting psychopathological risk." (PMID 33114535, 2020). "Hence, decreases in SLC6A4 methylation, as observed in this study, may be specifically associated with late-life depression." (PMID 30180828, 2018). "Similarly, the short form of 5-HTTLPR polymorphism of SLC6A4 was associated with reduced hippocampal volume in older adults with early onset depression (at a younger age) whereas the long form was associated with reduce hippocampal volume in older adults with late-onset depression." (PMID 26175754, 2015). "Genetic studies have also identified several other important genes beyond BDNF and SLC6A4 that influence both epilepsy and depression." (PMID 40941042, 2025). "Among the most studied genetic variants associated with depression is 5-HTTLPR, a polymorphism in the serotonin transporter gene (SLC6A4)." (PMID 40563330, 2025).
depression (continued). "This research was conducted to address a major gap in our understanding of the potential impacts on the placenta–brain axis in women prescribed SSRIs, which target Slc6a4/SERT to combat depression." (PMID 41516311, 2025). "For instance, reduced levels of BDNF and increased methylation of the SLC6A4 gene promoter have been notably correlated with the occurrence of major depression or a history of depression in patients with TLE." (PMID 39858450, 2025). "Key gene–environment interactions, including those involving serotonin transporter (SLC6A4) and inflammatory genes (e.g., TNF-α, IL-6), have been implicated in depression." (PMID 40428308, 2025). "The aim of this study was to investigate the association between the genetic type and alleles for the TPH1, TPH2, SLC6A4, HTR1A, HTR2A, and BDNF genes in Korean suicide attempters with major depressive disorder (suicide attempters) and a control group." (PMID 41300755, 2025). "In contrast, the connections between the 5-HTT gene’s epigenetic mechanisms and PPD are less understood, with one study showing associations with Edinburgh Postnatal Depression Scale scores and SLC6A4 promoter methylation during pregnancy." (PMID 39201521, 2024). "These alterations in DNA methylation, along with disrupted epigenetic control of genes, such as BDNF and SLC6A4, suggest a possible link between early life experiences, epigenetic changes, and increased vulnerability to depression." (PMID 39194576, 2024). "Specifically, the SLC6A4 gene was investigated in Vietnam veterans suffering from depression and some studies showed that psilocybin present in some mushroom species has antidepressant potential." (PMID 39338085, 2024). "Kang and colleagues analyzed the association among childhood adversity, the severity of depressive symptoms, and SLC6A4 methylation in patients with major depressive disorder (n = 108)." (PMID 38792892, 2024). "Variations in SLC6A4 are connected to traits such as anxiety and depression, which are also related to alcohol use disorder." (PMID 38491208, 2024). "The variants of the serotonin transporter (SLC6A4; SERT), dopa decarboxylase, and protein kinase C beta play roles in stressful life events, depression, and PPD onset." (PMID 37143780, 2023). "One of the most investigated genetic polymorphisms related to depression is 5-HTTLPR, a functional polymorphism in the promoter region of the serotonin transporter (5-HTT) encoding gene (SLC6A4)." (PMID 37558806, 2023). "DNA methylation modifications are associated with depression, with hypermethylation at sites encoding BDNF and SLC6A4." (PMID 37140907, 2023). "In particular, DNA methylation at multiple CpG sites in stress-related genes (e.g., NRC31, SLC6A4, and BDNF) was associated with depression and partially mediated the association between childhood maltreatment and depression." (PMID 36717542, 2023). "The SSRI, which inhibit serotonin transporter SERT/SLC6A4 (expressed in both neurones and astroglia) and thus increase bioavailability of serotonin, are probably the most widely used in the treatment of depression." (PMID 37828019, 2023). "Among these, the 5-HT2A receptor serves as a common drug target in the treatment of schizophrenia and of depression indirectly by blocking serotonin transporters (SERT and SLC6A4)." (PMID 37687205, 2023). "A review mentioned that DNA methylation modifications are associated with depression, with hypermethylation at sites encoding brain-derived neurotrophic factor (BDNF) and SLC6A4 (5-hydroxytryptamine transporter gene)." (PMID 37140907, 2023). "Genetic variants in both the serotonin transporter gene (SLC6A4, 5-HTT, or SERT) and in the catechol-O-methyltransferase (COMT) gene have been found to contribute to the pathophysiology of depressive disorder." (PMID 36833277, 2023). "Other targets such as ADRA1A, ADRB1, and SLC6A4 modify the occurrence of depression and other mental diseases." (PMID 35800440, 2022).